AKT1 (AKT serine/threonine kinase 1)
Diseases named in the same sentence as AKT1 in open-access papers (continued):
Sharing a sentence is not in itself a finding about the gene and the disease.
Insulin resistance (continued). "In this study, we generated skeletal muscle-specific Akt1/2 double-knockout mice and demonstrated that the knockout mice exhibited premature sarcopenic phenotypes, accompanied by systemic insulin resistance." (PMID 36198696, 2022). "For example, mutants of InR, chico, Dp110, Akt1, Rheb, and S6K disrupt the Insulin/TOR pathway and cause varying degrees of insulin resistance respectively." (PMID 36035393, 2022). "Recently in a proof-of-concept study, GELNs showed their potential in prevention of insulin resistance by restoring the expression of Foxa 2 by preventing AKT-1 mediated phosphorylation." (PMID 35795340, 2022). "According to our previous in vivo study, administration of baicalein led to an increased level of hepatic glycogen and upregulated phosphorylation of Akt1, consequently improving the insulin resistance and decreasing the expression of SOCS3." (PMID 32019168, 2020). "Palmitate plays a critical role in the initiation and development of insulin resistance as exposure of C2C12 cells to palmitate suppressed insulin-stimulated Akt1 phosphorylation and glucose uptake." (PMID 31266232, 2019). "It is theorised that impaired PI3K/Akt1/FOXO signalling and the resultant upregulation of PDK4 are important factors underlying the development of muscle insulin resistance." (PMID 25472724, 2014). "Akt1 is also nitrosylated at the residue C224 and is inactivated under pathogenesis of iNOS and/or oxidative stress-involved insulin resistance." (PMID 24887420, 2014). "In order to validate our model of insulin resistance, we measured Akt-1 Ser473 phosphorylation in HUVECs cultured in HG and Gluc-N for 72 h." (PMID 21297971, 2011). "Akt-1 and eNOS activation was reduced in conditions mimicking insulin resistance and completely restored by sildenafil treatment." (PMID 21297971, 2011). "Moreover, inhibition of PI3Kα-AKT1 was reported to induce energy expenditure in adipose tissue, suppress weight gain, and ameliorate insulin resistance in diet-induced obese mice." (PMID 40438591, 2025). "AKT1 signalling blocks the inhibitory effect of GSK3β on GS, and activated GS enables glycogen synthesis to reduce the production of endogenous glucose and alleviate insulin resistance." (PMID 39568571, 2024). "However, diabetes contributes to dysregulated AKT1 activity that leads to pancreatic beta cell apoptosis and insulin resistance, promoting metabolic deregulation and disease progression." (PMID 39707185, 2024). "Our results showed that GLP could regulate the TNF signaling pathway through AKT1; thus, it might reduce insulin resistance in patients with NASH." (PMID 35811658, 2022). "The AKT1 network plays physiological roles in the development of human diseases, including developmental and neurological disorders, cardiovascular diseases, cancers, inflammatory autoimmune disorders, and insulin resistance." (PMID 33572095, 2021). "Additionally, PRDM4, as the target gene of the PI3Kα-AKT1 signaling pathway, has been shown to increase energy expenditure, inhibit weight gain and improve insulin resistance." (PMID 33846573, 2021). "The possibility of whether the Akt1 isoform activates IKKα to create inflammatory feedback to insulin resistance mediated by Akt2 is plausible, but unknown." (PMID 28912810, 2017). "In diabetes mellitus and insulin resistance, insulin-mediated activation of eNOS viaPI3 kinase/AKT1 is inhibited, while the adverse effects of insulin remain unopposed, which may promote vascular disease." (PMID 24734227, 2014). "Thus, age-related alterations in hepatic gene expression and ectopic lipid accumulation associated with insulin resistance and T2DM are substantially reversed through skeletal-muscle-specific activation of Akt1 and the corresponding increase in muscle mass." (PMID 24033924, 2014). "However, a previous study showed that exercise only restored Akt1 expression in rats with HFD-induced insulin resistance, and Akt2 content was unchanged." (PMID 23272147, 2012).
Insulin resistance (continued). "However, in the context of chronic high-fructose intake, its potent lipogenic capacity induces lipotoxicity, which impairs the insulin-Akt1 signaling pathway and leads to insulin resistance, thereby shifting the primary regulation of DNL to alternative pathways such as ChREBP." (PMID 41415834, 2025). "This overexpression increases the uptake of glucose by muscle tissue and activated the PI3K/Akt-1 pathway by upregulating Akt-1 expression, which in turn leads to a decline in the expression levels of Foxo-1 and Pdk-4 to counteract the excess of glucose and inhibit the insulin resistance." (PMID 37584728, 2023). "Indeed, hepatic ablation of Akt1 and Akt2 contributes to glucose tolerance and insulin resistance." (PMID 25888638, 2015). "However, preclinical data suggest that parallel inhibition of both Akt1 and Akt2 could result in peripheral insulin resistance and drug-induced, dose-dependent hyperglycemia and hyperinsulinemia." (PMID 24281308, 2012). "Furthermore, due to damage to AKT1 signaling pathways, insulin cannot be effectively transported to the vascular system by the action of endothelial nitric oxide synthase (eNOS), leading to obesity and insulin resistance, followed by artery dysfunction and hypertension." (PMID 37664830, 2023). "SFFs also promoted the AKT-1 expression, which in turn inhibited GSK-3β expression and reduced insulin resistance." (PMID 35873798, 2022). "In the case of IRS1 (cg21511036), AKT1S1 (cg03813033), ADCY2 (cg12566890 and EHMT2 (cg00210002) are hypomethylated, whereas AKT1 (cg01749142), FOXO3 (15283498), are hypermethylated in subjects with insulin resistance and hypertriglyceridemia." (PMID 30926763, 2019). "Akt1 null (Akt1-/-) mice were protected from HFD-induced obesity and insulin resistance through enhanced energy expenditure." (PMID 30158592, 2018). "This insulin-induced hyper-phosphorylation of AKT1 and GSK-3β was significantly reduced in KO mice as assessed using western blotting, which implied that mild insulin resistance was induced in KO mice." (PMID 30485307, 2018). "Examination of the KEGG pathway for NAFLD (hsa04932) demonstrated transcriptional dysregulation of mediators of insulin resistance (IRS2, P1K3R1, AKT1), steatohepatitis ( JUN, ERN1) and neutrophil infiltration and inflammation (CXCL8)." (PMID 29786565, 2018). "Foxo1 liver ablation normalizes excessive glucose production and severe hepatic insulin resistance in animals lacking Akt1 and Akt2." (PMID 40141412, 2025). "While chronic IL6 elevation exacerbates insulin resistance, our data suggest context-dependent modulation where momordic acid’s stabilization of IL6 and AKT1 interactions may reconcile contradictory reports on cytokine function in metabolic regulation." (PMID 40283911, 2025). "In this regard, mice lacking both hepatic isoforms (Akt1:Akt2) show marked glucose intolerance and insulin resistance." (PMID 29709004, 2018). "Moreover, animal models of insulin resistance, including the obese Zucker rat, display defects in the PI3 kinase/AKT1 system and impaired NO bioavailability." (PMID 24734227, 2014). "Studies indicate that insulin resistance can be induced by stimulating the degradation of important molecules in the insulin signaling pathway, in particular the insulin receptor substrate proteins IRS1, IRS2 and the kinase AKT1 (Akt)." (PMID 19007436, 2008). "Additionally, dendrobine might affect cell signal transduction by influencing genes like AKT1, STAT3, potentially related to KEGG pathways such as “insulin resistance”, “PPAR signaling pathway”, and “insulin signaling pathway”." (PMID 38755697, 2024).
Insulin resistance (continued). "However, despite this relatively improved benefit of combining MK2206 and gefitinib in EGFR M+ cells, preclinical data using mouse models has shown that combined inhibition of both AKT1 and AKT2 can result in insulin resistance as well as hyperglycaemia and hyperinsulinaemia." (PMID 24946858, 2014). "Interestingly, this pathway is not inhibited in diabetes mellitus and insulin resistance; conversely, the insulin-mediated activation of eNOS viaPI3 kinase/AKT1 is inhibited, limiting its vasodilator and prosurvival function and therefore promoting vascular disease." (PMID 24734227, 2014).
glioma (466 papers, 2008 to 2026). A benign or malignant brain and spinal cord tumor that arises from glial cells (astrocytes, oligodendrocytes, ependymal cells). "All our results preliminarily confirmed that the loss of PDZK1 expression by siRNA inhibits glioma cell proliferation and induces cell apoptosis by preventing AKT1 phosphorylation." (PMID 38669103, 2024). "Gene mutations and copy number variations of MAPK1 and AKT1 in gliomas were analyzed using the cBioPortal for Cancer Genomics database." (PMID 38835342, 2024). "The network topology analysis performed in this study revealed a set of central nodes associated to glioma malignancy, such as Map3k14, Mapk1, Actn4, Hspa5, Atf2, Rac1,E2f1, Shc1, Pik3ca, Akt1, Vim and Egr1." (PMID 26582089, 2015). "AKT1 contains mutations, deep deletions, and amplifications in gliomas." (PMID 38835342, 2024). "In our experiment, AKT1 is another key target of sciadopitysin to promote apoptosis of glioma cell lines." (PMID 38911393, 2024). "First, to confirm the role of AKT1 in glioma, we analyzed TCGA data and found that AKT1 was overexpressed in glioma tissues." (PMID 38669103, 2024). "The potential top five genes of the anti-glioma effect of isocuB were identified by network pharmacology as RXRα, AKT1, ESR1, MAPK1, and HSP90AA1." (PMID 38835342, 2024). "The study also demonstrated that NSC-EXOs loaded with miR-124-3p effectively inhibited glioma growth by activating the EXO-miR-124-3p/FLOT2/AKT1 pathway." (PMID 39450275, 2024). "MiR-637 expression was shown to be downregulated in human gliomas, which was correlated with patients' poor prognoses and stimulated glioma development and invasion by activating Akt1." (PMID 39170516, 2024). "Overexpression of the AKT1 gene has been one of the common characteristics of glioma cells, as it promotes viability and malignancy." (PMID 38666818, 2024). "Western blotting was used to investigate the effect of PDZK1 knockdown on the AKT1/mTOR signaling pathway in glioma cells." (PMID 38669103, 2024). "We also confirmed the role of AKT1 in glioma by analyzing TCGA data and found that AKT1 was overexpressed in glioma specimens." (PMID 38669103, 2024). "The analysis revealed that the top five genes affected by isocuB in glioma were RXRα, AKT1, ESR1, MAPK1, and HSP90AA1." (PMID 38835342, 2024). "Consistently, a low level of AKT1 mRNA predicted poor prognosis in glioma patients, indicating that AKT1 plays a tumorigenic role in glioma." (PMID 38669103, 2024). "The result showed that Ser473 phosphorylated Akt1 expression by the western blot was markedly reduced in PANTR1 knockdown glioma cells, which plays an important role in cell death." (PMID 36861062, 2023). "IL-17 can mediate the recruitment of specific γδ T-cell subpopulations and activate the PI3K/Akt1/NF-κB-p65 pathway to promote glioma progression." (PMID 37889551, 2023). "These genes include HMGA1 in glioma, AKT1 in glioma, PTC, GC, and HCC, HEMGN in PTC, APLN and MMP19 in GC, WNT1 in CRC, NUPR1 in CRC and OSCC, LY6E and CTSB in CHOL, KLK4 and PLXNB2 in OC, and HDAC4 and STAT3 in SaOS." (PMID 36175921, 2022). "miR-637 inhibits the growth of tumor cell lines and tumor growth in xenograft animal models by targeting AKT1 in glioma and PDAC, LIF in HCC, and NUPR1 in OSCC." (PMID 36175921, 2022). "Low expression of miR-637 leads to up-regulation of the expression levels of HEMGN in PTC, NUPR1 in OSCC, and AKT1 in glioma and PDAC, thereby activating the PI3K/AKT signaling pathway and inhibiting the reproduction and growth of cancer cells." (PMID 36175921, 2022). "IL‐17 induces increased phosphorylation of Akt1 and NF‐κB‐p65, which, in turn, promotes glioma proliferation." (PMID 37786890, 2022).
glioma (continued). "The expression levels of p-PI3K and p-Akt1 in glioma cells treated with OSW-1 alone were significantly lower than those in the controls; however, OSW-1 combined with 740Y-P significantly increased these levels." (PMID 36133816, 2022). "It is therefore essential to investigate RIOK1 and AKT1 expression in glioma to identify new therapeutic approaches and prognostic biomarkers." (PMID 34475988, 2021). "RIOK1 and AKT1 mRNA levels were significantly higher in glioma patient tissues compared to normal brain tissues (TCGA-GBMLGG and GTEx databases), and their expression levels were significantly correlated (TCGA-GBMLGG databases, p<0.001, r=0.440)." (PMID 34475988, 2021). "The Kruskal–Wallis test confirmed a significant difference in methylation of all examined genes between glioma types (p < 0.001 for AKT1, AKT3, CHUK, GSK3β, EGFR, PTEN, PIK3AP1; p = 0.032 for AKT2)." (PMID 34209611, 2021). "It has been reported that the AKT1 protein and itsmRNA levels are similar in glioma and normal control tissues." (PMID 34455717, 2021). "Compared with normal tissues, RIOK1 and AKT1 expression were significantly upregulated in glioma tissues." (PMID 34475988, 2021). "MiR-637 decrease was related to poor overall survival and accelerated malignant properties of glioma cells by targeting AKT1." (PMID 34925640, 2021). "Our results demonstrate that RIOK1 and AKT1 expression are upregulated in glioma and correlate with poor prognosis." (PMID 34475988, 2021). "RIOK and AKT1 staining intensity were weak in normal tissues but increased in glioma samples in a WHO grade-dependent fashion." (PMID 34475988, 2021). "The results showed that RIOK1 and AKT1 protein levels were upregulated in glioma, with the highest expression in high-grade samples." (PMID 34475988, 2021). "In this study, we confirmed that RIOK1 and AKT1 levels significantly increased in GBM tissues and were positively associated with tumor malignancy, while knockdown of RIOK1 inhibits glioma cell growth through AKT1 and c-Myc in vitro." (PMID 34475988, 2021). "RIOK1 and AKT1 protein levels were determined by IHC in 106 glioma and 10 control samples using tissue microarrays." (PMID 34475988, 2021). "Correlation analysis of the western blot data showed that RIOK1 and AKT1 expression were significantly correlated in glioma samples (p<0.001, r=0.7084)." (PMID 34475988, 2021). "Sevoflurane also attenuated glioma cell proliferation and invasion thorough the upregulation of miR-637 and miR-124, which suppressed the Akt1 expression and ROCK1 signal pathways, respectively." (PMID 33919449, 2021). "Meanwhile, Circ-CFH was significantly upregulated in glioma tissue and was positively correlated with tumor grade, and it markedly increased the proliferative ability of glioma cells by specifically sponging miR-149 and releasing AKT1." (PMID 32061256, 2020). "The present study indicated that the expression level of the EGFR, ERK-1,2 and AKT-1,2 in glioma cell lines is medium and can induce cell growth in these cells." (PMID 33369441, 2020). "XL388-induced glioma cell death was only partially attenuated by a constitutively-active mutant Akt1." (PMID 33159013, 2020). "In the independent experiments we observed marked reductions of EGFR, ERK-1,2 and AKT-1,2 transcript in glioma cells in response to miR-4731 infection." (PMID 33369441, 2020). "Among the selected genes, 15 (Araf, Braf, Kras, Ccnd1, Cdk6, Igf1r, Nras, Pik3ca, Pik3r1, Pdgfra, Pdgfrb, Pdgfb, Akt1, Akt2, and Mdm2) were related to glioma and leukemia." (PMID 31523185, 2019). "To assess the clinical potential of our molecular findings, we first focused on glioma cell lines with high p-AKT1/ENTPD5 levels and investigated if a reduction in white matter invasion upon SPARC depletion improves survival in a pre-clinical setting." (PMID 31062076, 2019).